CD207 (CD207 molecule)
Description:
Calcium-dependent lectin displaying mannose-binding specificity. Induces the formation of Birbeck granules (BGs); is a potent regulator of membrane superimposition and zippering. Binds to sulfated as well as mannosylated glycans, keratan sulfate (KS) and beta-glucans. Facilitates uptake of antigens and is involved in the routing and/or processing of antigen for presentation to T cells. Major receptor on primary Langerhans cells for Candida species, Saccharomyces species, and Malassezia furfur. Protects against human immunodeficiency virus-1 (HIV-1) infection. Binds to high-mannose structures present on the envelope glycoprotein which is followed by subsequent targeting of the virus to the Birbeck granules leading to its rapid degradation.
Synonyms: CLEC4K; Langerin
Tractability: Small molecule: a structure with a bound ligand is known; it has a binding pocket of medium quality. Antibody: its Gene Ontology location is reachable by antibodies, with high confidence; UniProt predicts a signal peptide or a membrane-spanning region.
Target class: Membrane receptor
Gene: Protein-coding gene on chromosome 2 (70,830,211 to 70,835,816, reverse strand). Ensembl gene ENSG00000116031.
Subcellular location: Membrane
Subcellular location (Human Protein Atlas): Cytosol
Pathways (Reactome):
Immune System: Cross-presentation of soluble exogenous antigens (endosomes)
Gene Ontology:
Molecular function: carbohydrate binding; protein binding; D-mannose binding; pattern recognition receptor activity
Biological process: defense response to virus; immune response
Cellular component: clathrin-coated endocytic vesicle membrane; early endosome membrane; endocytic vesicle; external side of plasma membrane; plasma membrane; membrane
Genetic constraint (gnomAD): Loss-of-function variants: 27 observed, 30.89 expected, observed/expected ratio (o/e) 0.87, 90% interval 0.64 to 1.21. The upper end of that interval is the gene's LOEUF score, 1.21, which puts it in group 5 of 6, group 1 being the genes least tolerant of losing a copy. Missense variants: 380 observed, 401.64 expected, observed/expected ratio (o/e) 0.95, 90% interval 0.87 to 1.03. Synonymous variants: 165 observed, 155.94 expected, observed/expected ratio (o/e) 1.06, 90% interval 0.93 to 1.2.
Homologues: Orthologues: chimpanzee CD207 (98% identical), macaque CD207 (93% identical), pig CD207 (73% identical), rabbit CD207 (70% identical), guinea pig CD207 (69% identical), mouse Cd207 (66% identical), rat Cd207 (63% identical), Drosophila melanogaster tfc (17% identical), tropical clawed frog clec4m (17% identical), zebrafish asgrl1 (17% identical), tropical clawed frog asgr1 (16% identical), tropical clawed frog clec4e (16% identical), and 16 more. Paralogues in human: CLEC4F (32% identical), FCER2 (20% identical), CLEC17A (18% identical), ASGR1 (18% identical), ASGR2 (17% identical), CD209 (17% identical), CLEC4D (17% identical), CLEC10A (17% identical), CLEC4M (17% identical), CLEC4G (16% identical), CLEC4E (16% identical), CLEC4A (14% identical), and 2 more.
Diseases named in the same sentence as CD207 in open-access papers:
CD207 is named in the same sentence as 53 diseases in open-access papers, as found by Europe PMC text mining. Sharing a sentence is not in itself a finding about the gene and the disease. The quoted sentences say what the papers report.
Langerhans cell histiocytosis (43 papers, 2016 to 2025). Langerhans cell histiocytosis (LCH) is a systemic disease associated with the proliferation and accumulation (usually in granulomas) of Langerhans cells in various tissues. "Langerhans cell histiocytosis (LCH) is a rare systemic hematologic disorder caused by clonal expansion of myeloid precursors that differentiate into CD1a+/CD207+ dendritic cells in lesions that leads to a spectrum of organ involvement and dysfunction." (PMID 40416903, 2025). "Langerhans cell histiocytosis (LCH) is an inflammatory neoplasia resulting from clonal expansions of CD207 + CD1a + cells, which causes tissue destruction and a wide range of organ involvement." (PMID 38231288, 2024). "Langerhans cell histiocytosis (LCH) is a disease caused by clonal expansion of CD1a+/CD207+ cells and is characterized by organ involvement and dysfunction." (PMID 39935470, 2025). "Langerhans cell histiocytosis (LCH) is a rare disease caused by the clonal expansion of CD1a+/CD207+ LCH cells." (PMID 36246871, 2022). "Langerhans cell histiocytosis is a rare inflammatory neoplasm of myeloid origin characterized by the presence of classic CD1A+CD207+ histiocytes notorious for aberrant function secondary to activating somatic mutations in the MAPK (RAS–RAF–MEK–ERK) pathway." (PMID 40287907, 2025). "Langerhans cell histiocytosis (LCH), formerly called histiocytosis X, is the most frequent disease of the histiocytosis group and morphologically manifests itself by infiltration of organs by CD207+ cells with granuloma formation." (PMID 39337571, 2024). "Langerhans cell histiocytosis is a disease characterized by aggregation of CD1a+/CD207+ cells and inflammatory cell infiltration." (PMID 36177069, 2022). "Immunohistochemical stains highlighted expression of CD1a, Langerin (CD207) and S-100, consistent with the diagnosis of Langerhans cell histiocytosis." (PMID 29884166, 2018). "Langerhans cell histiocytosis (LCH) is a rare disease that is characterised by lesions that include CD207+ dendritic cells with phenotypic similarity to epidermal Langerhans cells on a background of inflammatory cells." (PMID 26631075, 2016). "Langerhans cell histiocytosis (LCH) is characterized by lesions that include CD1a+CD207+ dendritic cells, along with inflammatory cell infiltrates." (PMID 27833773, 2016). "Langerhans cell histiocytosis (LCH) is a disease originating from abnormal proliferation of CD1a+/CD207+ myeloid dendritic cells and characterized by activation of the mitogen-activated protein kinase (MAPK)/extracellular signal-regulated kinase (ERK) signaling pathway." (PMID 37551332, 2021). "Langerhans cell histiocytosis (LCH) is a rare inflammatory myeloid neoplasm characterized by organ infiltration by pathological myeloid dendritic cells that share surface markers with epidermal Langerhans cells (CD1a+/CD207+)." (PMID 32967635, 2020). "Langerhans cell histiocytosis (LCH) is a rare disease characterized by CD1a/CD207-positive dendritic cells." (PMID 40979825, 2025). "Langerhans cell histiocytosis (LCH) is a clonal, neoplastic proliferative disease characterized by the proliferation of immature dendritic cells (CD1a+/CD207+), leading to tissue and organ infiltration and subsequent functional impairments." (PMID 39346019, 2025). "Langerhans cell histiocytosis (LCH), the most common histiocytic disorder in children, features lesions of aberrant CD1a/CD207 (langerin)–expressing Langerhans cells with immune infiltrates." (PMID 41176307, 2025). "Langerhans cell histiocytosis (LCH) is an orphan disease characterized by clonal proliferation of abnormal CD1a+/CD207+ myeloid precursors cells." (PMID 35207181, 2022). "Langerhans cell histiocytosis (LCH) is a rare disease characterized by the accumulation of CD1a-positive (CD1a+)/CD207+ histiocytes with inflammatory lesions in various organ systems." (PMID 35379272, 2022).
Langerhans cell histiocytosis (continued). "Langerhans cell histiocytosis (LCH) is a rare disease characterized by clonal expansion of CD1a+/CD207+ cells in lesions." (PMID 35547871, 2022). "Langerhans cell histiocytosis (LCH) is a rare haematological neoplasm characterized by the accumulation of CD1a+, CD207/Langerin+ histiocytes within inflammatory lesions." (PMID 35915468, 2022). "Langerhans cell histiocytosis (LCH) is characterized by the accumulation of Langerin (CD207)-expressing histiocytes." (PMID 31527903, 2019). "Langerhans cell histiocytosis (LCH) lesions are defined by the presence of CD1a+/CD207+ myeloid cells, but many other immune cells are present including unconventional T cells, which have powerful immunoregulatory functions." (PMID 30405183, 2018). "Langerhans cell histiocytosis (LCH) is considered a neoplasia of Langerhans cells or a histiocytic tumor expressing S-100, CD1a and CD207." (PMID 28445138, 2017). "Langerhans cell histiocytosis (LCH) is a rare neoplasm characterized by the clonal proliferation of myeloid dendritic cells which express CD1a and CD207 (langerin)." (PMID 39873807, 2025). "Langerhans cell histiocytosis (LCH) is a rare disorder of unknown etiology, characterized by clonal proliferation of CD1a- and/or CD207-positive dendritic cells." (PMID 40979825, 2025). "Langerhans cell histiocytosis (LCH) is a rare myeloid neoplastic disorder characterized by the abnormal proliferation and accumulation of dendritic cells bearing the CD1a+/CD207+ phenotype." (PMID 40443606, 2025). "Langerhans cell histiocytosis, or LCH, is a haematological condition that results from the formation of granulomatous lesions, which are aggregates of langerin-positive (CD207+) histiocytes." (PMID 38657650, 2024). "Langerhans cell histiocytosis (LCH) is the most prevalent form of childhood histiocytosis, characterized by CD207-positive histiocytes that form granulomatous lesions accompanied by localized infiltration of inflammatory cells." (PMID 39767878, 2024). "Langerhans cell histiocytosis (LCH) is a neoplastic transformation of myeloid precursors characterized by the expression of CD1a, CD68, CD207 (Langerin), and S-100." (PMID 37522932, 2023). "Langerhans cell histiocytosis (LCH) is a rare, clonal disorder derived from CD1a-positive and CD207-positive immature myeloid dendritic cells, with a wide range of clinical presentations." (PMID 35841042, 2022). "Langerhans cell histiocytosis (LCH) is a rare myeloid neoplasm characterized by inflammatory lesions featuring pathological clonal infiltration of cells belonging to the mononuclear phagocyte system, which exhibit phenotypical traits resembling Langerhans cells, notably expressing CD1a and CD207." (PMID 39190425, 2024). "Off-label, some of them (vemurafenib, dabrafenib, trametinib, and cobimetinib) can be used in Langerhans cell histiocytosis (LCH) in children with the BRAFV600E mutation, a rare disease characterized by abnormal macrophage proliferation and granulomatous lesions composed of CD1a+CD207+ histiocytes." (PMID 38276485, 2023). "In the last decade, the gain-of-function BRAFV600E mutation was observed to be recurrent in the histiocytic disorders Langerhans cell histiocytosis (LCH) and Erdheim-Chester disease (ECD), characterized by the infiltration of CD1a+CD207+ and CD68+CD1a− clonal mononuclear phagocytes, respectively." (PMID 37673974, 2023). "Importantly, RDD histiocytes show negative staining for CD1a and CD207, which distinguishes RDD from Langerhans cell histiocytosis (LCH)." (PMID 40282877, 2025).
celiac disease (2 papers, 2016 to 2023). An autoimmune genetic disorder with an unknown pattern of inheritance that primarily affects the digestive tract. "The CD207 expression has been reported in the lamina propria of patients suffering of inflammatory bowel diseases or celiac disease, in kidneys, or in breast cancer, but it remains to be determined whether these cells are related to LCs or not." (PMID 27252701, 2016). "This also includes abnormal intrinsic tolDC function, only now being examined in coeliac disease, where increases in CD11c, CD103, CD207, and indoleamine 2,3-dioxygenase (IDO) are increasingly likely to play a role in celiac disease." (PMID 36851285, 2023).
COVID-19 (2 papers, 2022 to 2023). A disease caused by infection with severe acute respiratory syndrome coronavirus 2. "High levels of circulating GCNT4, RAB14, C1GALT1C1, CD207 and ABO have also been previously suggested to be causally associated with an increased risk of suffering from critical COVID-19, with comparable odds ratios varying from 1.12 to 1.35." (PMID 37958866, 2023).
Histiocytosis (2 papers, 2022 to 2024). An excessive number of histiocytes (tissue macrophages). "It was found that the stromal-like cells found in tissues affected by histiocytosis shared the phenotype characteristic for Langerhans cells (LCs), i.e. expression of langerin (CD207) and CD1a molecule." (PMID 38342891, 2024). "Another marker connected with histiocytosis progression is MMP-9, also identified in CD207 cells from LCH lesions." (PMID 38342891, 2024).
Rosai-Dorfman disease (2 papers, 2024 to 2026). "An immunohistochemical analysis demonstrated that the histiocyte-like cells were positive for S100 and CD68PGM1 and negative for CD1a and CD207, confirming the diagnosis of cutaneous Rosai-Dorfman disease (CRDD)." (PMID 42094958, 2026). "In the 2016 revised classification of histiocytoses, Rosai-Dorfman disease (RDD, also known as massive lymphadenopathy with sinus histiocytosis), was placed in the “R” group, which can be distinguished from “L” group (Langerhans) based on the absence of CD1a and CD207 expression." (PMID 39592527, 2024).
skin infection (2 papers, 2022 to 2024). An inflammatory process affecting the skin, caused by bacteria, viruses, parasites, or fungi. "S. aureus is associated with skin infections, and the receptor for this skin bacterium was recently described to be human CD207; however, it was unclear whether this mechanism of bacterial uptake is conserved between species." (PMID 39541348, 2024). "Further, patients with SNPs in CD207 of Langerhans cells or NLRP3 of phagocytes may be more prone to skin infections." (PMID 36636720, 2022).
acute myeloid leukemia (1 paper, 2023). Acute myeloid leukemia (AML) is a group of neoplasms arising from precursor cells committed to the myeloid cell-line differentiation. "In this study, we identified SE-associated genes by integrating cell-specific SEs with RNA-seq data and found six genes (CAPG, CD207, GPR132, SLC7A11, HIPK3 and FCER1G) that are correlated with poor prognosis in acute myeloid leukemia (AML) patients according to the TCGA-LAML database." (PMID 37296281, 2023).
asthma (1 paper, 2022). "In our study we found that OM–85 expanded the population of tolerance–associated CD207/langerin+CD103+ cDCs in the lung, here again recapitulating such finding found in asthma." (PMID 35603159, 2022).
autoimmune disease (1 paper, 2022). A disorder resulting from loss of function or tissue destruction of an organ or multiple organs, arising from humoral or cellular immune responses of the individual to their own tissue constituents. "Among some of the first studies on experimental models of autoimmune diseases, the utility of targeting the mannose receptor, DEC205, and mannose-, fucose-, and the n-acetylglucosamine-recognizing transmembrane protein, langerin (CD207), has been underlined." (PMID 36145531, 2022).
breast tumor (1 paper, 2020). "In patients, heavy infiltration of primary breast tumor with CD207+Langerin+ immature DCs are a common pathological feature and, while their presence does not directly affect prognosis in themselves, it is likely they are blunting the immune response to immunotherapies." (PMID 32937885, 2020).
Crohn disease (1 paper, 2022). A gastrointestinal disorder characterized by chronic inflammation involving all layers of the intestinal wall, noncaseating granulomas affecting the intestinal wall and regional lymph nodes, and transmural fibrosis. "Paraformaldehyde-fixed intestinal tissues, obtained from fifteen patients with Crohn’s disease were analyzed by immunostaining for serotonin, Langerin/CD207, and alpha-Smooth Muscle Actin (α-SMA)." (PMID 35453516, 2022).
dry eye (1 paper, 2018). "Genetically engineered mice have been characterized as models for chronic forms of dry eye; these include the Aire mice and Langerin (CD207) deficient mice." (PMID 29407221, 2018).
emphysema (1 paper, 2026). "Collectively, these findings demonstrate that CD207+ DCs orchestrate a pathogenic CD8+ T-cell response in emphysema and represent a promising therapeutic target." (PMID 41498703, 2026). "In patients with COPD, the abundance of CD207+ DCs in small airways correlates with both emphysema severity and lung function decline (FEV1%pred)." (PMID 41498703, 2026). "This study identifies CD207-positive dendritic cells (CD207+ DCs) as pivotal mediators of emphysema progression." (PMID 41498703, 2026). "In a murine emphysema model, adoptive transfer of CD207+ DCs reversed the attenuation of emphysema, inflammation and CD8+ T-cell expansion in CD207-knockout mice." (PMID 41498703, 2026).
experimental autoimmune encephalomyelitis (1 paper, 2022). An autoimmune demyelinating disease of the central nervous system that is produced experimentally in animals by the injection of homogenized brain or spinal cord in Freund's adjuvant. "In previous work, despite reduced numbers of CD207+EPCAM+ migratory DCs detected in the DLNs of ACKR2-/- mice at day 3 post immunization with antigen, deficiency of ACKR2 did not impair T-cell priming and subsequent development of experimental autoimmune encephalomyelitis." (PMID 36518752, 2022).
Granuloma (1 paper, 2017). A compact, organized collection of mature mononuclear phagocytes, which may be but is not necessarily accompanied by accessory features such as necrosis. "Histologic examination of a pre-therapy lymph node biopsy specimen revealed non-caseating granulomas with sheets of CD1A−/CD207−/fascin+/CD163+/factorXIII−/PGM1+ histiocytes." (PMID 28512266, 2017).
HIV-1 infection (1 paper, 2021). The type species of lentivirus and the etiologic agent of acquired immunodeficiency syndrome (AIDS). "In steady-state conditions LCs form a protective barrier against HIV-1 infection by capture of HIV-1 via C-type lectin receptor langerin (CD207) and subsequent degradation via TRIM5α-mediated autophagy." (PMID 33568786, 2021).
hypospadias (1 paper, 2019). Hypospadias is the displacement of the urethral meatus on the ventrum of the penis. "The mean frequency of epidermal HLA-DR/CD207 double positive cells per mm2 accounted to 873.4 ± 61.6 in patients with hypospadias (n = 21) as compared to 940.2 ± 84.2 in patients without penile malformation (n = 12, p = 0.522, t-test)." (PMID 31718599, 2019).
invasive carcinoma (1 paper, 2024). A carcinoma that is not confined to the epithelium, and has spread to the surrounding stroma. "Other differentially expressed transcripts include S100A7, LCN2, CXCL14, and CD207 (decreasing expression from premalignant lesions to invasive carcinoma), as well as IDO1, IL6, IL8, THBS1, and FN1 (increasing expression from premalignant lesions to invasive carcinoma)." (PMID 38706595, 2024).
juvenile xanthogranuloma (1 paper, 2017). A benign histiocytic tumor that occurs during childhood; it is distinct from Langerhans cell histiocytosis. "Juvenile xanthogranuloma (JXG) is a rare non-Langerhans cell (LCH) histiocytic disorder with histologic features characteristic of dermal dendrocytes (fascin+, CD1a−, CD207−) and macrophages (CD14+, CD68+, CD163+, and factor XIIIa+)." (PMID 28512266, 2017).
lung carcinoma (1 paper, 2020). "In a different study, the gene CD207 (that encodes for langerin) was identified as a specific marker for tumor-associated cDC2s, both in mouse and human lung cancers." (PMID 32486257, 2020).
Lyme disease (1 paper, 2025). Lyme disease (named after the towns in the USA where the disease was first identified) is a bacterial infection caused by Borrelia burgdorferi. "We therefore investigated the frequencies of cutaneous CD207+ LCs in the erythema migrans lesion centers of patients with cutaneous Lyme disease, which form at the site of prior tick bite and compared them to autologous, non-lesional skin." (PMID 41315257, 2025).
monocytopenia (1 paper, 2019). "Their shortened survival, lympho- and monocytopenia, absence of Leydig cells, and thymic and splenic atrophy were nearly identical to BrafCATg(CD207-cre) mice." (PMID 31527903, 2019).